ADM (adrenomedullin)
Diseases named in the same sentence as ADM in open-access papers (continued):
Sharing a sentence is not in itself a finding about the gene and the disease.
pheochromocytoma (33 papers, 2009 to 2025). "Adrenomedullin, encoded by ADM gene, is a peptide initially isolated from human pheochromocytoma tissues and described as a hypotensive factor." (PMID 38690165, 2024). "MR-proADM is a stable fragment of the precursor molecule of adrenomedullin (ADM), a peptide originally discovered in human pheochromocytoma tissue." (PMID 41155371, 2025). "Adrenomedullin (ADM) is a member of the calcitonin gene‐related peptide (CGRP) family of proteins that was isolated for the first time from human pheochromocytoma cells and exerts an important hypotensive effect." (PMID 40387073, 2025). "Adrenomedullin (ADM), a peptide hormone, was first identified and isolated from a human pheochromocytoma in 1993." (PMID 40565016, 2025). "ADM is a 6-kilodalton (52 amino acid) peptide hormone isolated in 1993 from a pheochromocytoma whose gene is located at a single locus on chromosome 11 and consists of four exons and three introns." (PMID 38891025, 2024). "Adrenomedullin (ADM) is a 52-amino acid peptide that was initially isolated from human pheochromocytomas with structural similarities to calcitonin gene-related peptide (CGRP)." (PMID 38190401, 2024). "Adrenomedullin (ADM) is a hormone isolated in 1993 from pheochromocytoma cells but synthesized ubiquitously in the body, whose main function is vasodilation and preservation of endothelial barrier integrity." (PMID 38891025, 2024). "Adrenomedullin (ADM) is a peptide that was originally isolated from pheochromocytoma and is widely distributed in the body." (PMID 37408575, 2023). "Adrenomedullin is a biologically active peptide isolated from human pheochromocytoma tissue and known to have various physiological functions, such as angiogenesis, organ protection, and anti‐inflammatory activity." (PMID 36799102, 2023). "Adrenomedullin (ADM) is a peptide hormone isolated in 1993 by Kitamura from extracts of a pheochromocytoma." (PMID 36836567, 2023). "Since this peptide is abundant in normal adrenal medulla, as well as pheochromocytoma tissue, it was called ADM." (PMID 36836567, 2023). "Human adrenomedullin mRNA is highly expressed in several tissues, including adrenal medulla, ventricle, lung, kidney, and vessel walls as well as pheochromocytoma, adrenomedullin peptide circulates in the blood at a considerable concentration." (PMID 36139120, 2022). "Adrenomedullin (ADM) is a neurohormonal peptide first discovered in pheochromocytoma-derived tissue in 1993." (PMID 34173962, 2022). "Adrenomedullin (ADM) is a 52-amino acid peptide hormone that was originally identified in extracts of human pheochromocytoma." (PMID 35355972, 2022). "Adrenomedullin (ADM) is a peptide hormone that belongs to the calcitonin gene-related peptide family and was first isolated from phaeochromocytoma tissue at the end of the 20th century." (PMID 35326373, 2022). "Adrenomedullin (ADM) is a potent vasodilator peptide with 52-amino acid residues originally isolated from human pheochromocytoma, and its action is mediated by calcitonin receptor-like receptor (CRLR)." (PMID 35324977, 2022). "Adrenomedullin (ADM) is a 52-amino acid peptide hormone first discovered in human pheochromocytoma cells, but is produced by many different cell types." (PMID 33148300, 2020). "Adrenomedullin was discovered in 1993 from human pheochromocytoma and was regarded as one of the major circulating vasodilator peptides with therapeutic potential." (PMID 28620317, 2017). "Adrenomedullin (ADM) is a peptide that was first isolated from the acid extract of human pheochromocytoma." (PMID 27376090, 2016). "Adrenomedullin (ADM) is a vasodilator peptide that was originally isolated from the extract of human pheochromocytoma in 1993." (PMID 26557147, 2015). "Adrenomedullin was originally isolated from pheochromocytoma cells and reduces insulin resistance by decreasing oxidative stress." (PMID 25028667, 2014).
pheochromocytoma (continued). "Adrenomedullin (ADM) is a small, secreted signaling peptide first identified in a pheochromocytoma of the human adrenal gland and belongs to the calcitonin gene–related peptide family." (PMID 22690112, 2012). "Adrenomedullin (ADM) is a peptide of 52 amino acids and was originally isolated from human pheochromocytoma cells and has later been detected in other tissues, including heart, adrenal medulla, lungs, and kidneys." (PMID 19627611, 2009). "Adrenomedullin (ADM), a vasodilator peptide hormone induced by hypoxia, was initially isolated in 1993 from a phaeochromocytoma." (PMID 39985422, 2025). "Adrenomedullin (ADM), initially isolated from a pheochromocytoma tissue, is a ubiquitous peptide present in physiological conditions in vascular, renal, adipose, pulmonary and cardiac tissue." (PMID 36012430, 2022). "Adrenomedullin (ADM), a potent and long-lasting vasoactive peptide, was originally isolated from human pheochromocytoma in 1993." (PMID 28348718, 2017). "Adrenomedullin (ADM), as a 52-amino-acid regulatory peptide, was initially isolated from human pheochromocytoma." (PMID 24099554, 2013). "Adrenomedullin (ADM), a 52-amino acid peptide, was originally isolated from human pheochromocytoma and initially shown to have potent vasodilatory activity." (PMID 21595896, 2011). "Adrenomedullin (ADM) is a 52-amino acid hormone belonging to the amylin/calcitonin gene-related peptide (CGRP) super-family, that has been originally identified in the extracts of human pheochromocytoma." (PMID 34150648, 2021). "Adrenomedullin (ADM), a 52-amino acid ringed-structure peptide with C-terminal amidation, is a newly discovered member of the calcitonin peptide family; it was originally isolated from human pheochromocytoma." (PMID 23841075, 2013).
pancreatic cancer (28 papers, 2009 to 2026). "The most persuasive explanation for the frequent occurrence of DM in conjunction with pancreatic cancer is as a paraneoplastic condition caused by tumor-secreted products, such as adrenomedullin." (PMID 29718860, 2018). "Additionally, compared to the general population, patients with diabetes caused by pancreatic cancer had higher levels of adrenomedullin, according to a clinical study." (PMID 38835644, 2024). "In vitro studies indicate that adrenomedullin impairs glucose-stimulated insulin secretion in β-cells, and adrenomedullin overexpression in mouse pancreatic cancer tissues is associated with increased glucose intolerance suggesting that adrenomedullin is an important mediator of cancer-induced DM." (PMID 25426078, 2014). "Previous studies have highlighted dysregulation of adrenomedullin in various types of tumors such as osteosarcomas, pancreatic cancer, prostate cancer, and gastric cancer." (PMID 40547013, 2025). "As an angiogenic factor, ADM is highly expressed in various tumor tissues, including hepatocellular carcinoma, oral squamous cell carcinoma, and pancreatic cancer." (PMID 40565016, 2025). "ADM22-52, an ADM antagonist, functions by competing with ADM for receptor binding and has been utilized in various tumor models, such as breast cancer, pancreatic cancer, and mesothelioma, to counteract ADM activity." (PMID 40565016, 2025). "One of the main mediators of beta-cell toxicity in a pancreatic cancer cell-line study was found to be adrenomedullin." (PMID 38835644, 2024). "Pancreatic cancer cells also promote lipolysis in subcutaneous adipocytes through a mechanism based on exosomal adrenomedullin." (PMID 37481560, 2023). "In pancreatic cancer tissues, ADM, KRT17, and ANXA1 protein levels surpassed those in normal samples, while C7 and ALB protein levels exhibited a declining trend, in accordance with the findings from qRT-PCR and bioinformatics analysis." (PMID 37941546, 2023). "Knocking down ADM has been shown to reduce myelomonocytic cell recruitment and tumor angiogenesis in pancreatic tumor-bearing mice." (PMID 37941546, 2023). "In the pancreatic cancer microenvironment, pancreatic cancer cells and fibroblasts produce adrenomedullin to inhibit adipocyte response to insulin signals." (PMID 35252207, 2022). "Further, a clinical study reported that the levels of adrenomedullin are higher in patients with pancreatic cancer-induced diabetes in comparison to general population." (PMID 35222270, 2022). "Adrenomedullin was identified as one of the key mediators for beta-cell toxicity in a cell-line study of pancreatic cancer." (PMID 35222270, 2022). "Adrenomedullin mediates the inhibition of insulin secretion in β-cells in pancreatic cancer patients, and its level is higher in patients with pancreatic cancer than in patients with T2DM without pancreatic cancer." (PMID 35625546, 2022). "Knockdown of ADM in pancreatic tumor-bearing mice significantly inhibited the recruitment of myelomonocytic cells and tumor angiogenesis." (PMID 35002712, 2021). "Pancreatic cancer cells secrete high levels of adrenomedullin (ADM) that binds myelomonocytic cells to enhance their migration, invasion, and activity of MMP-2 in vitro." (PMID 35008355, 2021). "Of these genes, we have observed that adrenomedullin (ADM) exhibits the worst prognosis in pancreatic cancer." (PMID 31217513, 2019). "In the present review, we focuses on the interplay between adipocytokines, gut microbiota, adrenomedullin, hyaluronan, vanin and matrix metalloproteinase affected by metabolic alteration and pancreatic tumor progression." (PMID 30567565, 2018). "ADM has been previously reported to be overexpressed in several types of cancer, such as colorectal cancer, pancreatic cancer, clear cell renal cell carcinoma (RCC) and so on." (PMID 27391260, 2016). "Here, we demonstrate that the level of ADM expression negatively correlates with disease-free survival in pancreatic cancer patients." (PMID 27391260, 2016).
pancreatic cancer (continued). "Taken together, these results demonstrate that ADM negatively correlates with prognosis of pancreatic cancer and positively correlates with the abundance of myelomonocytic cells in human pancreatic cancer tissues." (PMID 27391260, 2016). "Strikingly, Kaplan-Meier survival curve demonstrated that pancreatic cancer patients with high ADM levels had poor disease free survival, indicating that ADM was a prognostic factor for pancreatic cancer." (PMID 27391260, 2016). "Collectively, these results provide another insight for how ADM contributes to pancreatic cancer growth and unravelling a promising way for pancreatic cancer treatment." (PMID 27391260, 2016). "The expression levels of ADM in pancreatic cancer tissues positively correlated with the density of CD11b+ cells (r=0.7302)." (PMID 27391260, 2016). "In the present study, we observed that the level of ADM expression correlates positively with the density of myelomonocytic cells in human pancreatic cancer tissues." (PMID 27391260, 2016). "Similar to other pro-angiogenic factors like VEGFA and PlGF secreted by tumor cells, ADM promotes pancreatic cancer growth through stimulating tumor angiogenesis and recruiting myelomonocytic cells." (PMID 27391260, 2016). "In the present study, pancreatic cancer cells secreted high levels of adrenomedullin (ADM), and CD11b+ myelomonocytic cells expressed all components of ADM receptors, including GPR182, CRLR, RAMP2 and RAMP3." (PMID 27391260, 2016). "To further confirm the clinical significance of ADM expression, we analyzed the pancreatic cancer data set and discovered that mRNA levels of ADM were significantly higher in pancreatic cancer tissues than those in adjacent normal tissues." (PMID 27391260, 2016). "ADM is highly expressed in a variety of malignancies such as glioblastoma, clear-cell renal carcinoma and pancreatic cancer." (PMID 22859951, 2012). "We previously showed that adrenomedullin (AM) is over-expressed in pancreatic cancer and has a strong autocrine role in this disease." (PMID 19847298, 2009). "Adrenomedullin (AM) is highly expressed in pancreatic cancer and stimulates pancreatic cancer cells leading to increased tumor growth and metastasis." (PMID 19847298, 2009). "Reversely, the release of adrenomedullin, a possible mediator of beta cell dysfunction, is increased in pancreatic cancer and may lead to early diabetes." (PMID 38835644, 2024). "Our investigation revealed that, with the exception of ADM, the mRNA expression patterns of the remaining six model genes were consistent with the findings of our bioinformatics analysis in at least one of the pancreatic cancer cell lines." (PMID 37941546, 2023). "In fact, it has been reported that sEVs derived from pancreatic cancer carry a bioactive peptide called adrenomedullin, which is involved in the breakdown of lipids in adipose tissue, and may contribute to the decomposition of lipids in sEVs." (PMID 33915936, 2021). "Additionally, the protein levels of ADM in the plasma of patients with different types of cancer, pancreatic cancer included, were significantly higher than those in healthy people." (PMID 27391260, 2016). "In summary, these findings provide a new insight into the roles of ADM in pancreatic cancer and how interruption of these processes may provide a novel and potentially effective way to treat pancreatic cancer." (PMID 27391260, 2016). "Our observations revealed that ADM and ERRG exhibited significantly elevated total expression levels in human tumor tissues, with expression patterns in all seven pancreatic cancer cases aligning with our predictions." (PMID 37941546, 2023). "Among them, the mRNA levels of ADM, C4orf3, ERO1L, FUT11, BNIP3L, NDRG1, KCTD11, SLC2A1, and P4HA1 were increased in pancreatic cancer tissues compared to adjacent pancreatic tissues from TCGA and GTEx database." (PMID 34221996, 2021).
pancreatic cancer (continued). "High expression levels of ADM led to poor outcomes in patients, which is consistent with previous findings that ADM is over expressed in PDAC and enhances pancreatic cancer cell invasion." (PMID 31217513, 2019). "We selected the marker genes (ADM, ERO1A, ENO2, BNIP3, and UPP1) of CAF-C2 to detect their expression in human pancreatic CAF-stellate cell (CAF118), human pancreatic cell (HPC-Y5), and human pancreatic cancer cell line." (PMID 36544710, 2022). "We also correlated ADM levels with clinicopathological status of pancreatic cancer patients and found that mRNA levels of ADM did not correlate with gender, age, or stage of lymph node metastasis." (PMID 27391260, 2016).
breast carcinoma (27 papers, 2003 to 2026). "In breast cancer, clinical evidence supports this notion, as higher ADM protein levels are significantly associated with axillary lymph node metastasis." (PMID 40547013, 2025). "The strongest association observed was for circulating pro-adrenomedullin concentrations and breast cancer risk (OR 1.19, 95% CI 1.10–1.29; q-value = 0.033)." (PMID 38301482, 2024). "In “Discovery analyses” examining potential novel inflammatory marker-cancer pairs, we found strong evidence for an association of genetically-proxied pro-adrenomedullin concentrations with breast cancer risk." (PMID 38301482, 2024). "The interesting finding was that the late phase of breast cancer metastasis was associated with a rise in ADM and fall in ADN plasma concentration." (PMID 30683749, 2019). "The role of adrenomedullin in bone metastases was tested by stable overexpression in MDA-MB-231 breast cancer cells, which cause osteolytic bone metastases in a standard animal model." (PMID 25439669, 2014). "In conclusion, we have shown for the first time that ADM peptide is widely expressed in breast cancer and that the degree of expression is associated with lymph node metastasis." (PMID 14612905, 2003). "We then analysed if there were associations between ADM expression in breast cancer tissue or blood and the clinico-pathological properties of patients." (PMID 14612905, 2003). "In addition to its physiological role, adrenomedullin is implicated in the pathogenesis of several malignancies, including breast cancer and melanoma." (PMID 38690165, 2024). "Similarly, the ADM-HIF-1α axis had been implicated in enhancing chemoresistance in breast cancer." (PMID 40529377, 2025). "Breast cancer cell-derived adrenomedullin (ADM) enhances the expression of UCP1 in adipocytes and promotes the phosphorylation of hormone-sensitive lipase (HSL), thereby stimulating lipolysis and the browning of adipocytes." (PMID 41498391, 2026). "Multiple factors contribute to adipocyte browning in breast cancer, including molecules like exosomes and adrenomedullin secreted by breast tumour cells and metabolic changes in the breast tumour microenvironment." (PMID 41498391, 2026). "In breast cancer models, tumour-derived adrenomedullin (ADM), a hypoxia-inducible peptide, drives UCP1 expression in adjacent adipocytes through paracrine signalling." (PMID 40943351, 2025). "Research indicates that both mRNA and protein levels of ADM are markedly elevated in breast cancer tissues, with a strong correlation to low histological differentiation and the presence of axillary lymph node metastasis." (PMID 40565016, 2025). "In breast cancer research, it has been demonstrated that ADM is among the factors derived from CAFs that facilitate the recruitment of endothelial-like cells and pericytes for neovascularization." (PMID 40565016, 2025). "As breast cancer progresses, characterized by increasing tumor size and advancing clinical stage, serum levels of ADM in patients also rise correspondingly." (PMID 40565016, 2025). "For example, ADM was identified to be downregulated in BRCA, contrasting with studies linking ADM to increased tumor aggressiveness in various breast cancer subtypes." (PMID 40529377, 2025). "Here we show that breast cancer mammospheres expressed ADM, while ADM receptors were highly expressed in lipid-laden cells obtained after differentiation of adipose progenitors (AP), including breast APs." (PMID 32819314, 2020). "Given that solid tumors usually exhibit low oxygen tension, many express and secrete ADM, as measured in high-grade breast cancer patients." (PMID 32819314, 2020). "Our results also revealed that plasma ADM levels positively correlated with the malignancy in breast cancer and colorectal cancer." (PMID 27391260, 2016). "In this study, we have examined ADM peptide expression in breast cancers by means of a newly characterised monoclonal antibody." (PMID 14612905, 2003).